APOE (apolipoprotein E)
Diseases named in the same sentence as APOE in open-access papers (continued):
Sharing a sentence is not in itself a finding about the gene and the disease.
neurodegenerative disease (continued). "The impact of the APOE genotype on the transport of HDL particles, cognition and its connection with the development of neurodegenerative diseases has been reviewed by other authors." (PMID 36153580, 2022). "To demonstrate the potential of this technique for understanding the pathogenesis of neurodegenerative disease, we applied our SILK technique to determine the effect of ATP binding cassette A1 (ABCA1) on both apoE and Aβ clearance." (PMID 22512932, 2012). "We also compared amyloid-β A4 protein levels between APOE ε4 carriers and noncarriers across neurodegenerative diseases to determine if the plasma APOE ε4 signature was related to amyloid-β pathology." (PMID 40665049, 2025). "The APOE ε4 proteomic signature remained independent of neurodegenerative disease status and sex, with CART models showing strong predictive power for carrier status." (PMID 40665049, 2025). "Strategies to modulate SDC function, disrupt lipid raft integrity, or target specific ApoE–SDC interactions could reduce the internalization and aggregation of toxic proteins, potentially slowing or halting the progression of neurodegenerative diseases." (PMID 40362276, 2025). "Understanding the molecular basis of ApoE–SDC interactions provides new insights into the spread of pathological proteins and offers potential therapeutic strategies for targeting these interactions in the treatment of neurodegenerative diseases." (PMID 40362276, 2025). "Our results demonstrate that all APOE ε4 carriers, irrespective of neurodegenerative disease, have a unique proteome signature that extends across the plasma and CSF." (PMID 40665049, 2025). "Although none of the neurodegenerative disease groups showed a relationship between APOE ε4 and angiopathy, there was a small statistically significant association found in nonimpaired controls." (PMID 40665049, 2025). "Conversely, one study proposes that suppressing TREM2 activation in neurodegenerative disease may be protective, since TREM2 signaling through the TREM2–Apolipoprotein E (ApoE) axis drives microglia toward the MGnD phenotype and promotes neuronal loss." (PMID 41465422, 2025). "The molecular and genetic interactions of ApoE with amyloid proteins have been extensively studied in neurodegenerative diseases, but have not yet been well connected and clarified." (PMID 36817952, 2023). "APOE, CST3, and CLU are known to be mainly involved in all three neurodegenerative diseases and, in particular, have a function of binding to amyloid-β or tau protein, indicating an association with features of neurodegenerative diseases due to protein aggregation of misfolded proteins." (PMID 36797805, 2023). "Of these APOE, APOC1 and ASAH1 are involved in lipid metabolism and neurodegenerative diseases." (PMID 35388616, 2022). "We examined whether the ApoE‐dependent recovery induced by EA involves the Nrf2/ NQO1/HO‐1 signaling pathway, which mitigates oxidative stress in certain neurodegenerative diseases." (PMID 34423582, 2021). "Ethnic differences in brain aging are likely due in large part to genetic factors; thus, we compared carriers and non-carriers of a gene relevant to longevity and neurodegenerative diseases, such as apolipoprotein E (APOE) ε4." (PMID 32903525, 2020). "Pharmacological targeting of TREM2 to suppress the inflammatory response and modifying ApoE ɛ4 isoform via CRISPA/cas9 may provide a new approach for developing therapeutic strategies in the treatment of neuroinflammation and other neurodegenerative diseases." (PMID 30909239, 2019). "Apolipoprotein E (ApoE) is increasingly recognized as an influential if not determining host factor in neuroinflammatory and neurodegenerative disease." (PMID 28321820, 2017). "Notably, these changes were independent of neurodegenerative disease and sex, suggesting that APOE ε4 carriers share a common molecular phenotype." (PMID 40665049, 2025).
neurodegenerative disease (continued). "A key limitation is the lack of longitudinal data for nonimpaired APOE ε4 carriers, who may later develop neurodegenerative disease." (PMID 40665049, 2025). "In the following sections, we will discuss the pathophysiology of major neurodegenerative diseases, AD, and PD, from the perspective of APOE’s non-protagonist role in pathophysiological processes (i.e., amyloid homeostasis, Tau phosphorylation, synuclein pathologies)." (PMID 39596597, 2024). "Interestingly, we also found that in addition to the upregulated expression of genes related to microglial inflammatory activation (H-2 gene), genes related to neurodegenerative diseases, such as CD74 and APOE, were also upregulated in the hypothalamus of mice in the cystic fluid group." (PMID 35525962, 2022). "TREM2 is one of the major receptors of ApoE, the interactions between ApoE and TREM2 are important in the context of AD pathogenesis, and the TREM2–ApoE pathway has been reported to be a major regulator of the microglial functional phenotype in neurodegenerative diseases." (PMID 35582645, 2022).
tumor (331 papers, 1998 to 2026). "Flow cytometry and IF staining demonstrated that TAMs were also associated with increased APOE expression in the tumor core." (PMID 40745073, 2026). "We identified a subpopulation of tumor cells with lower expression levels of APOE in both mRNAs and proteins that were highly associated with more advanced stages and metastasis of PTC by integrating single‐cell sequencing and spatial transcriptome assays." (PMID 39810624, 2025). "We identified a subpopulation of tumor cells with lower expression levels of APOE, associated with advanced stages of PTC and cervical metastasis." (PMID 39810624, 2025). "A comprehensive analysis of the four sets of differentially expressed genes indicated that the low expression of ApoE in tumours is linked to the regulation of the innate immune response." (PMID 40662483, 2025). "This approach is particularly promising for APOE-overexpressing cancers (where our cohort data show association with tumor relapse), as it simultaneously targets resistance mechanisms while exploiting BRCA-deficient vulnerabilities." (PMID 41390817, 2025). "High APOE expression was found to be positively associated with advanced tumor stage and higher Gleason scores across multiple cohorts." (PMID 40365288, 2025). "Spermine was found to drive the polarization of tumor-associated macrophages into an APOE+ immunosuppressive phenotype, thereby modulating the tumor immune microenvironment." (PMID 40963562, 2025). "To investigate the effect of ApoE deficiency on tumour growth in subcutaneous tumours, we conducted a series of experiments." (PMID 40662483, 2025). "Through transcriptomic sequencing analysis of tumours in WT and ApoE−/− mice, we observed that ApoE deficiency resulted in decreased expression levels of the immunologically relevant genes CCL24, CD74, and CX3CR1." (PMID 40662483, 2025). "Tumor macrophages demonstrated significant upregulation of genes associated with polarization to the tumorigenic and immunosuppressive M2 phenotype (e.g., APOE, CD163, WNT5A, and THBS1)." (PMID 40848148, 2025). "They found that non-invasive cell lines carry ApoE ε3/ε3 or ε3/ε4 alleles, while invasive cell lines carry APOE ε2/ε4 alleles, indicating that APOE variants are associated with intracellular cholesterol imbalance and tumor aggressiveness." (PMID 41343534, 2025). "Specifically, we revealed that the less‐SPP1+ Mph and APOE+ Mph cells in patients with low EDEM3‐expressed tumours was associated with the best response." (PMID 39754316, 2025). "Nonetheless, this approach presents a potential limitation, as hyperlipidemic conditions, such as those in ApoE-deficient or other hyperlipidemic mouse models, restrict tumor development." (PMID 39851526, 2025). "APOE is implicated not only in tumor metabolism and immune modulation but also in tumor invasion and metastasis." (PMID 40365288, 2025). "Among them, TAM-APOE represented the tumor-associated macrophages with high expression levels of APOE, CD163, and VSIG4." (PMID 39107908, 2024). "APOE+ Tumor‐associated macrophages (TAMs) are a subset of macrophages that exhibit immunosuppressive properties and are known to promote tumour progression." (PMID 39187937, 2024). "A study of apolipoprotein E (ApoE) showed that tumor-associated macrophage (TAM)-derived exosomal ApoE prompted the activation of the PI3K/Akt signaling pathway within recipient GC cells." (PMID 39719600, 2024). "We validate our findings through immunofluorescence analysis of colorectal cancer samples with a particular focus on examining FOLR2+APOE+ macrophages, which have previously demonstrated a positive prognostic association in breast cancer." (PMID 39034339, 2024). "Apolipoprotein E (ApoE) has been indicated to be expressed predominantly by tumor-associated macrophages (TAM) or cancer-associated fibroblasts in the tumor in mice or humans." (PMID 39695088, 2024).
tumor (continued). "Metabolism-related genes such as AHSG, ALB, and APOE gradually increased in expression during the mid-late stage of development, indicating their stronger association with abnormal tumor metabolism." (PMID 38230205, 2024). "High APOE expression is observed in myeloid cells, especially in tumor-associated macrophages (TAMs) and fibroblasts." (PMID 37958351, 2023). "Many conserved interactions involved tumour ligands associated with ER stress, such as APOE, IL11 and CCL2." (PMID 37612508, 2023). "Whilst some studies associate APOE with tumor progression, another study proposes APOE as a potential protective factor." (PMID 38067270, 2023). "Altogether, these results show that the Macro_APOE/CTSZ abundance associates with high‐grade tumor in patients with CRC by contributing to immunosuppressive TME." (PMID 36587392, 2023). "A murine model using wild-type mice showed that APOE upregulation was also associated with enlarged tumor sizes." (PMID 38067270, 2023). "In GC, a research revealed the mechanism by which exosome-mediated APOE proteins are transferred from tumor-associated macrophages to tumor cells." (PMID 38054821, 2023). "Based on the available data, we found that most cancer types overexpress APOE, and clear associations exist between the expression level of APOE and prognosis in tumor patients." (PMID 37304007, 2022). "The liver X nuclear receptor (LXR)/apolipoprotein E (ApoE) axis has been implicated in enhancing anti-tumor activity." (PMID 36131911, 2022). "The frequency of APOE ε4 allele and the E3/E4 genotype was relatively greater in tumor or CVD patients (P < 0.001)." (PMID 36057714, 2022). "The lymph node metastasis and TNM staging are associated with overexpression of ApoE in PC tissues, thus reflecting the tumor progression." (PMID 36506554, 2022). "For instance, heterogeneity of APOE+ tumor-associated macrophages (TAM, c19) were exhibited by the complementary distribution of C1QC+ and SPP1+ cells, which is consistent with a previous report on pan-cancer scRNA-seq analysis." (PMID 36333338, 2022). "ApoE ε3/ε3 genotype was also associated with 1.9-fold increased odds of developing LSCC T4 tumor (OR = 1.867 95% CI = 1.067–3.267; p = 0.029)." (PMID 35892323, 2022). "Ablating ApoE in mice inoculated with tumor cells enabled tumor cell rejection and was associated with induction of immune pathway activation and immune cell infiltration." (PMID 36341364, 2022). "In vivo analysis showed that sh-APOE significantly impaired tumor growth and tumor weight in xenograft mouse models caused by sh-FTO." (PMID 35090515, 2022). "This implies that there is a common underlying mechanism for APOE in regulating tumour occurrence and development." (PMID 33521130, 2021). "In ApoE-deficient tumor-bearing mice, circulating and intra-tumor MDSCs were higher than the control and led to faster tumor growth." (PMID 34742349, 2021). "The inhibitory effect of ApoE KO on tumor development and metastasis was associated with increase of infiltration of NK cells." (PMID 31275318, 2019). "Following the in vivo studies, we investigated the role of ApoE in tumor development-related signaling pathways associated with cell cycle, metastasis, and apoptosis." (PMID 31275318, 2019). "The exosomes-mediated transfer of functional ApoE protein from tumor-associated macrophages to tumor cells promoted the migration of GC cells by triggering the activation of PI3K/Akt signaling pathway." (PMID 30876419, 2019). "ApoE overexpression was associated with aggressive biological behaviors and poor prognosis in a variety of tumor according to previous studies." (PMID 30631342, 2018). "A recent study has shown that ApoE was associated with tumor advanced grade and stage in gastric carcinomas and involved in invasion, metastasis and carcinogenesis." (PMID 30631342, 2018). "Clinically, on the basis of gene expression analysis, ApoE has been identified as a potential tumor-associated marker in GC9,43." (PMID 29567987, 2018).
tumor (continued). "The possible biological mechanisms of the association between APOE ε4 genotype and carcinoma of the proximal colon and breast is subjects carrying APOE ε4 genotype less than half of the risk of tumor cell proliferation." (PMID 25029444, 2014). "ApoE, another protein specifically identified in 4T1-MDSCs, has been associated with depth of tumor invasion, degree of lymph node metastasis, and with clinical stage." (PMID 21853032, 2011). "We used unconditional logistic regression to evaluate the associations between ApoE SNPs, tumour MSI status, and dietary factors after adjusting for age and sex." (PMID 19455140, 2009). "The higher percentage of CD68 and APOE double-positive areas in the tumor core compared to the tumor edge and peritumoral normal tissue indicates that macrophages are also associated with the increased APOE in the tumor microenvironment, especially within the tumor core." (PMID 40745073, 2026). "Previous studies have reported an association between APOE and tumor progression in solid tumors." (PMID 41390817, 2025). "However, our study has not fully explored the precise molecular mechanisms underlying APOE’s influence on the tumour immune microenvironment." (PMID 39810624, 2025). "One proposed hypothesis is that high ApoE expression could be associated with decreased tumour cell invasion and an enhanced immune response." (PMID 40662483, 2025). "The fact that APOE+ macrophages are consistently linked to tumor progression across multiple cancers suggests they may have a conserved, pro-tumorigenic function." (PMID 40432828, 2025). "This indicates that ApoE deficiency may create a more immunosuppressive microenvironment that promotes tumour growth." (PMID 40662483, 2025). "Lastly, APOE-high myeloid cells showing immunosuppressive phenotype are most active with respect to outgoing signals, notably expressing genes associated with tumor growth, EMT, angiogenesis, and immune suppression in metastatic TME." (PMID 40835684, 2025). "Additionally, monocytes and particularly tumor-associated macrophages (TAMs) (LAM2 APOE + macrophages and SIGLEC1 + macrophages) were prominently closer to EMT hotspots as compared to EPI hotspots." (PMID 39529126, 2024). "In addition, our study examined the possible characteristics of tumours that cause the invasion of CD14+APOE+ cells." (PMID 39187937, 2024). "The role of the APOE alleles and their genotypes varies across different tumor types." (PMID 39763652, 2024). "To assess whether Macro_APOE/CTSZ was associated with histologic grade of the tumor, we found these immunosuppressive markers were significantly upregulated in high‐grade tumors compared with low‐grade in CRC‐MMRp and CRC‐MMRp." (PMID 36587392, 2023). "However, the underlying mechanisms by which APOE influences tumor growth and metastasis remain unexplored in our study." (PMID 38054821, 2023). "APOE polymorphisms may hence serve as a guide for identifying individuals at risk of tumor so as to design precise preventive strategies and therapies." (PMID 36057714, 2022). "In addition, knockout or suppressed ApoE expression can also downregulate cyclin D1 and its associated proteins, thereby hampering the tumor proliferation and migration." (PMID 36506554, 2022). "However, the effect exerted by APOE within tumor immunization responses especially in tumor-associated macrophages (TAM) is still not tackled down." (PMID 36147474, 2022). "The reason might be that the loss of APOE led to the reduction of M2 macrophages and thus reshaped the tumor immune microenvironment, which is more conducive to killing cancer cells." (PMID 36147474, 2022). "Study also suggests that tumor-associated M2 macrophages in GC can produce exosomes containing functional ApoE, which mediate the transfer of ApoE-stimulated PI3K/AKT signaling pathway to recipient GC cells, resulting in the pro-migratory phenotype of the tumor cells." (PMID 36506554, 2022).